RANBP1 (RAN binding protein 1)
Description:
Plays a role in RAN-dependent nucleocytoplasmic transport. Alleviates the TNPO1-dependent inhibition of RAN GTPase activity and mediates the dissociation of RAN from proteins involved in transport into the nucleus (By similarity). Induces a conformation change in the complex formed by XPO1 and RAN that triggers the release of the nuclear export signal of cargo proteins. Promotes the disassembly of the complex formed by RAN and importin beta. Promotes dissociation of RAN from a complex with KPNA2 and CSE1L (By similarity). Required for normal mitotic spindle assembly and normal progress through mitosis via its effect on RAN. Does not increase the RAN GTPase activity by itself, but increases GTP hydrolysis mediated by RANGAP1. Inhibits RCC1-dependent exchange of RAN-bound GDP by GTP.
Synonyms: HTF9A
Tractability: Small molecule: a structure with a bound ligand is known; it has a high-quality binding pocket. PROTAC: UniProt records ubiquitination sites on it; ubiquitination databases record sites on it; its protein half-life has been measured.
Gene: Protein-coding gene on chromosome 22 (20,115,877 to 20,127,355, forward strand). Ensembl gene ENSG00000099901.
Subcellular location (Human Protein Atlas): Cytosol
Pathways (Reactome):
Disease: Rev-mediated nuclear export of HIV RNA
Gene Ontology:
Molecular function: cadherin binding; GDP-dissociation inhibitor activity; protein binding; small GTPase binding
Biological process: nuclear export; signal transduction; nucleocytoplasmic transport
Cellular component: cytoplasm; cytosol; nuclear envelope; nuclear pore; nucleus
Genetic constraint (gnomAD): Loss-of-function variants: 16 observed, 31.9 expected, observed/expected ratio (o/e) 0.5, 90% interval 0.34 to 0.76. The upper end of that interval is the gene's LOEUF score, 0.76, which puts it in group 3 of 6, group 1 being the genes least tolerant of losing a copy. Missense variants: 265 observed, 374.32 expected, observed/expected ratio (o/e) 0.71, 90% interval 0.64 to 0.78. Synonymous variants: 129 observed, 142.22 expected, observed/expected ratio (o/e) 0.91, 90% interval 0.79 to 1.05.
Homologues: Orthologues: chimpanzee RANBP1 (100% identical), macaque RANBP1 (100% identical), rabbit RANBP1 (68% identical), pig RANBP1 (67% identical), mouse Ranbp1 (67% identical), rat Ranbp1 (66% identical), guinea pig RANBP1 (66% identical), rat Ranbp1l1 (63% identical), Drosophila melanogaster Nup358 (29% identical), Caenorhabditis elegans npp-9 (27% identical). Paralogues in human: RANBP2 (32% identical), RGPD1 (25% identical), RGPD4 (25% identical), RGPD2 (25% identical), RGPD3 (25% identical), RGPD5 (24% identical), RGPD6 (24% identical), RGPD8 (24% identical), RANBP3 (17% identical), RANBP3L (15% identical).